EGFR (epidermal growth factor receptor)
Diseases named in the same sentence as EGFR in open-access papers (continued):
Sharing a sentence is not in itself a finding about the gene and the disease.
mucositis (23 papers, 2014 to 2026). Mucositis is inflammation and damage of the mucous membranes lining the mouth and other parts of the gastrointestinal (GI) tract. "Although mono-therapy with anti EGFR antibodies or TKi causes few mucosal lesions, these drugs are often associated to cytotoxic agents that cause an increase in mucositis incidence and severity." (PMID 33028357, 2020). "Anti-EGFR agents also tended to increase the risk of mucositis (OR = 1.58 [95% CI: 0.99–2.52], P = 0.06)." (PMID 29254252, 2017). "However, treatment with anti-EGFR is associated with high incidence of mucositis and, to a lesser degree, electrolyte imbalances, notably hypomagnesaemia." (PMID 40722718, 2025). "Indeed these cancer treatments are, associated with a higher incidence of all-grade mucositis compared to other EGFR-TKi (40% vs. 15% of all-grade, 8.7 vs. 1% of grade ≥ 3) or to anti-EGFR monoclonal antibodies therapy." (PMID 33028357, 2020). "Moreover, the addition of anti-EGFR agents increased the risk of skin toxicities (odds ratio = 4.04 [95% CI: 2.51–6.48], P < 0.00001) and mucositis (odds ratio = 1.58 [95% CI: 0.99–2.52], P = 0.06)." (PMID 29254252, 2017). "EGFR inhibitors used in cancer treatment may cause a broad spectrum of dose-dependent cutaneous adverse events, including acneiform papulopustular rash, nail and hair disturbances, xerosis, and mucositis." (PMID 36708507, 2023). "A rat RIOM model validated HDZJF efficacy by assessing mucositis severity, inflammatory cytokines, and EGFR/PI3K/AKT pathway protein expression." (PMID 40129983, 2025). "Evidence suggests that the incidence of mucositis increases with concomitant administration with EGFR inhibitors such as cetuximab and panitumumab." (PMID 35954563, 2022). "Overall grade 3–4 toxic events were comparable between the two arms; however, anti-EGFR therapy related toxicities like skin reaction and mucositis significantly varied between the investigational and control arms during IC and RT." (PMID 29580204, 2018). "Though rare, SJS/TEN should be distinguished from EGFR inhibitor-related mucositis, particularly when the patient present with constitutional symptoms and widespread atypical target spots with blisters that extend beyond mucosa to the skin." (PMID 29577050, 2018). "The incidence of EGFR inhibitor-induced cutaneous adverse drug reactions (cADRs) is high (36%–80%), of which most were papulopustular eruptions, xerosis, paronychia, mucositis, and photosensitivity." (PMID 29577050, 2018). "For Cetuximab, mucositis and diarrhea may result from EGFR inhibition in the GI epithelium, which impairs mucosal repair and absorption." (PMID 40630125, 2025). "Building on this, we hypothesize that HDZJF may improve radiation-induced mucositis by modulating multiple key molecules, such as EGFR, PI3K, AKT, and downstream targets like NF-κB, BAX, and BCL-2." (PMID 40129983, 2025). "Interestingly, the incidence of oral mucositis was higher (all grades: about 30–40%, grade 3 or higher: approximately 10%) when the anti-EGFR antibody was used in combination with 5-fluorouracil (5-FU), which is a well-known mucotoxic drug." (PMID 30290786, 2018). "However, the AEs spectrum of the anti-EGFR and paclitaxel combination is not comparable to that for TPF as grade 3–4 AEs mainly involved skin toxicity and mucositis and only led to treatment discontinuation in 11.8% of patients." (PMID 35936723, 2022).
tuberculosis (23 papers, 2014 to 2025). A chronic, recurrent infection caused by the bacterium Mycobacterium tuberculosis. "At the clinical and epidemiological level, patients with previous or concurrent tuberculosis have a higher incidence of LC, a worse prognosis, and specific molecular alterations, such as EGFR mutations." (PMID 41322988, 2025). "Specific mutations, including EGFR, have been identified in patients with prior tuberculosis, influencing both prognosis and therapeutic response." (PMID 41322988, 2025). "This case report discusses an unusual presentation of epidermal growth factor receptor (EGFR)-mutated non-small-cell lung cancer (NSCLC) initially mimicking tuberculosis (TB), complicated by pituitary involvement." (PMID 40556846, 2025). "Treatment for the coexistence of epidermal growth factor receptor (EGFR)-mutant pulmonary adenocarcinoma and tuberculosis remains unclear." (PMID 33663064, 2021). "Using an EGFR inhibitor in a murine model of infection, we show the relevance of EGFR signaling in vivo and demonstrate that targeting the host with compounds already in clinical use for other applications holds potential for novel therapeutics for tuberculosis." (PMID 24586159, 2014). "Unlike the PDE inhibitors however, the liver X receptor inhibitor, ABL inhibitor, TGF-beta inhibitor, GPR109A inhibitor, and now an EGFR inhibitor all have efficacy even in absence of traditional tuberculosis therapy." (PMID 24586159, 2014).
autoimmune disease (22 papers, 2011 to 2025). A disorder resulting from loss of function or tissue destruction of an organ or multiple organs, arising from humoral or cellular immune responses of the individual to their own tissue constituents. "Other data in the literature indicate that an altered EGF/EGFR/ERK pathway is involved in the exacerbation of chronic inflammation in other autoimmune diseases, such as SLE and psoriasis." (PMID 39768182, 2024). "MAPK signaling activated by Rab7a phosphorylation may be a response to post-infectious inflammation, and Rab7a may be a new target for the control of LPS/EGFR-mediated inflammation and autoimmune diseases." (PMID 36344490, 2022). "Furthermore, EGFR involved in autoimmune diseases, is a target of Lapatinib, approved for the treatment of HER2-positive metastatic BC and other drugs included in preclinical and clinical trials." (PMID 36556228, 2022). "Patients were excluded from the trial if they were harboring EGFR mutations or ALK translocations, had an Eastern Cooperative Oncology Group (ECOG) performance status ≥2, had untreated brain metastasis, or were receiving any dose of oral steroids for an autoimmune disease." (PMID 28285592, 2017). "Therefore, interaction with EGFR may be the common mechanism by which FhHDM-1 prevents the development of distinct autoimmune diseases." (PMID 27883079, 2016). "Therefore, all patients with NSCLC without a contraindication (e.g., autoimmune diseases) or an actionable driver mutation (e.g., epidermal growth factor receptor [EGFR], anaplastic lymphoma kinase [ALK], or c‐ros oncogene 1 [ROS1]) should receive a PD(L)1i as part of their first‐line treatment." (PMID 35499294, 2022). "PV is a complex autoimmune disease with Dsg3 being a central player in pemphigus acantholysis that likely is triggered by a collection of signaling pathways, including Src, p38 MAPK, EGFR, c-Myc, and Rho GTPases, downstream of PV-IgG targeting Dsg3 disruption." (PMID 31582719, 2019).
colon adenocarcinoma (22 papers, 2009 to 2024). "Results showed that VANGL1 and EGFR proteins were overexpressed (more than 50% of the stained cells in colon adenocarcinoma tissues compared with the normal tissues)." (PMID 33672900, 2021). "A recently described 180-gene predictor assay was found to significantly classify EGFR-inhibitor-treated lung and colon adenocarcinoma disease types into high and low response groups." (PMID 26980732, 2016). "Upon knockdown of DSG2, DSC2 has been shown to be upregulated in colonic adenocarcinoma cell lines, and this might explain why we can still observe a positive adhesiotropic effect of EGFR or SRC inhibition upon Dsg2 knockdown." (PMID 36795511, 2023). "For example, in colon adenocarcinoma, highly sensitive techniques and application of anti-EGFR therapy have made it possible to detect up to 70% of Ras mutations in blood in series where the percentage diagnosed in the primary tumor was approximately 40–45% based on standard molecular techniques." (PMID 31970428, 2020). "During preparation of our manuscript, Yang and co-workers reported generation of a knock-in mouse expressing EGFR tagged with the Emerald fluorescent protein, which was exploited to study the localization of EGFR in normal mouse tissues and carcinogen-induced colon adenocarcinoma." (PMID 29268862, 2017). "Lung and colon adenocarcinomas show KRAS mutations in a subset of tumors, particularly in codon 12 and 13, and these tumors harboring KRAS mutation are associated with resistance to anti-EGFR directed therapeutic approaches." (PMID 26053092, 2015). "Enhanced activity of AP-1 has been demonstrated in human colon adenocarcinoma and the immune-histochemical analysis of majority of colon adenocarcinoma has revealed high-level expression of AP-1 correlating with the high expression of its downstream targets like EGFR and COX-2." (PMID 25157570, 2014). "The transmembrane glycoprotein located at the cell surface named epithelial growth factor receptor-EGFR is presented in different tumor cell lines such as SW480 (stage II) and SW620 cell lines derived from a colon adenocarcinoma and a lymph node metastasis." (PMID 37630022, 2023). "Known Hsp90 clients EGFR, HER2, CDK4, CDK6, CXCR4, Akt-1, c-Raf, Survivin, ERK-5 and Integrin α2 were analyzed following the administration of KUNB31 to HT29 (colon adenocarcinoma grade II) cells." (PMID 29382832, 2018).
malignant pleural mesothelioma (22 papers, 1990 to 2026). A malignant neoplasm that arises from mesothelial cells in the pleura and shows a diffuse growth pattern. "The activity of a miR-16 mimic delivered by bacterial minicells targeted to EGFR (TargomiRs) was then evaluated in a phase 1 study of patients with recurrent malignant pleural mesothelioma, showing a partial response in one out of 22 evaluable patients." (PMID 35352023, 2022). "Epidermal growth factor receptor (EGFR) is commonly overexpressed in malignant pleural mesothelioma (MPM)." (PMID 22922885, 2012). "Delivery of miR-16 using an EnGeneIC Delivery Vehicle (EDV) nanocell system targeting epidermal growth factor receptor (EGFR) in NSCLC and malignant pleural mesothelioma resulted in significant tumor reduction." (PMID 35628648, 2022). "The binding efficiency of 67Ga-Nimotuzumab in MRC-5 (cells with basal levels of EGFR), A431 (cells with EGFR-overexpression), and MSTO-211H (malignant pleural mesothelioma) cells was 6.9 ± 0.3%, 34.5 ± 1.9%, and 21.6 ± 1%, respectively." (PMID 30501113, 2018).
medullary thyroid cancer (22 papers, 2009 to 2025). "Although EGFR overexpression is frequently seen in medullary thyroid cancer, EGFR mutations are rarely described." (PMID 26294908, 2015). "Vandetanib is an anti-EGFR TKI that is approved for the treatment of advanced medullary thyroid cancer." (PMID 35908023, 2022). "Vandetanib is an EGFR TKI that has been approved for the treatment of patients with advanced medullary thyroid cancer." (PMID 35908023, 2022). "Vandetanib, a FDA-approved medullary thyroid cancer therapy that inhibits EGFR, impairs the HIF-1 pathway by targeting the mTOR–HIF-1α–VEGF signaling axis in breast cancer cells and increases survival in advanced medullary thyroid carcinoma." (PMID 34041023, 2021). "Vandetanib, selectively targeting RET, VEGFR, and EGFR tyrosine kinases, has been approved for the treatment of medullary thyroid carcinoma (MTC)." (PMID 28740507, 2017). "Tenascin C, EGFR, E-cadherin, TTF-1-expression, and their correlations with RET mutation status were investigated in 30 patients with medullary thyroid carcinoma (MTC) (n = 26) or C-cell hyperplasia (n = 4)." (PMID 27409604, 2016). "Epithelial lung, pancreatic, colorectal, head and neck, and medullary thyroid cancer all have a subset of patients whose cancers are driven by dysregulation of epidermal growth factor (EGF) secretion and/or overexpression/mutation of epidermal growth factor receptor (EGFR)." (PMID 37754956, 2023). "Vandetanib is an oral multi-TKI that inhibits RET, EGFR (Epidermal Growth Factor Receptor), and VEGFR-2/3, and is approved for the treatment of medullary thyroid carcinoma." (PMID 39199650, 2024). "Two cases of cornea verticillata after treatment with vandetanib (i.e., a dual anti-EGFR and vascular endothelial growth factor receptor 2 (VEGFR2) tyrosine kinase inhibitor) for medullary thyroid carcinoma were reported." (PMID 39518366, 2024). "Vandetanib, targeting VEGFR, epidermal growth factor receptor (EGFR), RET, for medullary thyroid cancer." (PMID 34956857, 2021). "Vandetanib targets both EGFR and VEGFR tyrosine kinases and was indicated for the treatment of symptomatic or progressive medullary thyroid cancer (MTC) in patients." (PMID 32595510, 2020). "Interactions between EGFR and chimeric forms of RET found in 30-50% of sporadic medullary thyroid cancers (RET/PTCs) have been reported by Croyle et. al.." (PMID 28460442, 2017). "Vandetanib, which inhibits VEGF receptor dependent tumor angiogenesis and epidermal growth factor receptor (EGFR-) and RET-mediated tumor cell proliferation, along with cabozantinib, is now FDA approved for treatment of medullary thyroid cancer." (PMID 26064704, 2015). "For instance, vandetanib, a tyrosine kinase inhibitor targeting the RET, vascular endothelial growth factor receptor (VEGFR), and epidermal growth factor receptor (EGFR), has been approved by FDA as a drug for medullary thyroid cancer." (PMID 26679379, 2015). "Vandetanib, a small-molecule tyrosine inhibitor targeting vascular endothelial growth factor receptor (VEGF) and epidermal growth factor receptor (EGFR) as well as RET kinase, is commonly used to treat locally advanced or metastatic inoperable medullary thyroid carcinoma." (PMID 37376154, 2023). "Although ZD-6474, also known as Vandetanib, targeting EGFR, has not been approved for treatment of NSCLC, it has been used in medullary thyroid cancer." (PMID 24369726, 2013).
cervical tumors (21 papers, 2008 to 2025). "EGFR is also associated with the growth of tumor cells and functions as an immune-suppressor factor to promote cervical tumor growth through the STAT3 pathway." (PMID 40336816, 2025). "Overexpression of EGFR protein in cervical tumours has been reported to be associated with poor prognosis, although in some studies, including the present study, this association is less clear." (PMID 21730982, 2011). "We also examined the EGFR activation upon EGF treatment in cervical tumor-derived cell lines CaSki and HeLa, as before." (PMID 36255238, 2022). "In the present work, we showed that EGFR, uPA, and TM levels of human cervical tumors correlated with worse overall patient survival and that uPA and TM were positively regulated by EGFR." (PMID 33886813, 2021). "In the present work, we observed a positive expression correlation between EGFR and several fibrinolytic system elements, including uPA and TM on human cervical tumor samples, with prognostic significance." (PMID 33886813, 2021). "In the present work, EGFR, uPA, and TM expression had a positive correlation on human cervical tumor samples, and the high expression of these genes was associated with worse patient overall survival." (PMID 33886813, 2021). "Epidermal growth factor receptor (EGFR) is a receptor tyrosine kinase widely expressed in cervical tumors, being correlated with adverse clinical outcomes." (PMID 33392068, 2020). "Our data suggest a close correlation between chemoresistance and EGFR activation in cervical tumor and PMC." (PMID 28796259, 2017). "Over expression of EGFR, frequently assessed only by IHC, is commonly seen in 2/3 of cervical tumour samples." (PMID 22091418, 2011). "EGFR inhibition also remains a privileged target of investigations in cervical tumours, based on the link between EGFR activation and resistance to radiation and platinum-based chemotherapy." (PMID 22091418, 2011). "It is possible that HPV-positive penile cancers, similar to cervical tumours, rely on E5 dependent, EGFR-driven cell proliferation only in the early stages of the disease." (PMID 21407808, 2011). "EGFR overexpression (2+ or 3+) was found in 64% (34/53) of the primary cervical tumors and 60% (32/53) of the corresponding lymph node metastases." (PMID 18700025, 2008). "EGFR overexpression (2+ or 3+) was found in 64% (35/53) of the primary cervical tumors and 60% (32/53) of the corresponding lymph node metastases." (PMID 18700025, 2008). "Inhibition of EGFR signaling significantly impedes growth of cervical tumors." (PMID 35008200, 2021). "From the literature, it is known that cervical tumors often present with variable levels of EGFR." (PMID 27783105, 2017). "Additionally, it was reported that CEMIP could induce tumor angiogenesis via interacting with the EGFR pathway of cervical tumors in a NF-κB dependent manner." (PMID 35957875, 2022). "Analysis of markers in cervical tumour specimens before RT have shown that hypoxia as well as increased survival signalling through Her-2, epidermal growth factor receptor (EGFR) or insulin-like growth factor receptor (IGFR) are predictive for lack of RT response." (PMID 19672258, 2009). "However, it is unclear whether metastases lose, gain, or retain EGFR status relative to the primary cervical tumors." (PMID 18700025, 2008). "RhoB expression is induced by EGF, PDGF, and many other agents, while several factors including N-Ras and EGFR suppress RhoB promoter activity in NIH3T3 cells and human cancer cell lines derived from lung, pancreatic, and cervical tumors." (PMID 31331053, 2019).
cervical tumors (continued). "In conclusion, our data provide a clear rationale for the use of UCB-NK to treat cervical tumors and also the possibility of using PBNK in combination with CET for EGFR-expressing tumors, with both significantly higher cytotoxicity and degranulation levels than in PBNK only conditions." (PMID 27783105, 2017).